VDR (vitamin D receptor)
Diseases named in the same sentence as VDR in open-access papers (continued):
Sharing a sentence is not in itself a finding about the gene and the disease.
cancer (continued). "We highlight some differences of VDR growth control relevant to colonic, esophageal, prostate, pancreatic and other cancers and assess the potential for development of selective prevention or treatment strategies." (PMID 19737544, 2010). "A reduction in the expression of the VDR in carcinomas indicates lower sensitivity of the tissue to Vitamin D control." (PMID 20831823, 2010). "VDR is a key nuclear receptor controlling transcriptional activation of multiple genes in response to inflammation, oxidative stress and cancer in CNS." (PMID 19426536, 2009). "Vitamin D and cancer: calcitriol, the biologically active form of vitamin D (1,25(OH)D), exerts its effects mainly through binding to nuclear vitamin D receptor (VDR)." (PMID 22276021, 2009). "Only a handful of studies have comprehensively analyzed genetic variation in the VDR gene in relation to cancer." (PMID 19753122, 2009). "The results obtained in this study add to the evidence for a role of VDR as an important mediator in the development of cancer." (PMID 19105801, 2008). "The methylation level of the LOH-H cancers was significantly lower at the 5'-transitional CpG sites of the VDR, FLJ43855, CDKN2A, MUC8, MAGEA2, and MSLN genes." (PMID 16827945, 2006). "Finally, we discuss current evidence for VDR targeting across cancer, metabolic disease, fibrosis, and immune-inflammatory disorders, including mechanisms of resistance such as dysregulated vitamin D metabolism and epigenetic repression." (PMID 41897332, 2026). "The worse condition of larger nodule and multinodularity require further VDR expression to impede the disease progression that may lead to further nodule formation or developing to malignant tumor." (PMID 40008182, 2025). "In cancer cells, VDR expression increased significantly, while TNFα remained unchanged." (PMID 41444742, 2025). "These interactions underscore VDR’s role as an integral node in the complex network governing BA signaling and its impact on immunity, particularly within the intestinal microenvironment relevant to inflammation and cancer." (PMID 40821794, 2025). "Disruption of VDR function may contribute to the onset of various serious conditions, such as cancer, psoriasis, rickets, renal osteodystrophy, and autoimmune diseases." (PMID 39861482, 2025). "However, calcitriol-treated ATC cell lines revealed reduced proliferation, pointing to the possible use of VDR agonists in the management of this aggressive cancer." (PMID 40071065, 2025). "VDR acts as a transcriptional regulator whose activity has been extensively studied using techniques such as ChIP-seq, which have identified thousands of binding sites throughout the human genome, many of them related to autoimmune diseases and cancer." (PMID 41301826, 2025). "This could be attributed to how VDR gene polymorphisms affect the expression and functionality of the vitamin D receptor, impacting cell proliferation, differentiation, and immune response, all critical in cancer progression." (PMID 40356850, 2025). "In conclusion, this comparative cross-sectional study demonstrates that the highest expression levels of the cancer stem cell marker CD44 and cytoplasmic VDR are significantly associated with aggressive histological types of EOT, particularly in patients with HGSC in FIGO stages III or IV." (PMID 40332380, 2025). "VDR/vitamin D binding in cancer cells prevents tumor growth and induces apoptosis." (PMID 40071065, 2025). "Finally, we examined the nonparametric Spearman’s correlation between the expressions of the examined CSC markers, VDR, cancer grade, and FIGO stage in OCs." (PMID 40332380, 2025).
cancer (continued). "In conclusion, variations in the efficacy of vitamin D3 could be due to (a) differences in the cell number, exposure time, and methods of assessment of viability and apoptosis; and/ or (b) the variations in VDR expression among different cancer cell types." (PMID 40920750, 2025). "In addition, activation of the VDR can lead to increased expression of proapoptotic Bax protein and downregulation of anti-apoptotic Bcl-2, which promotes apoptosis of cancer cells." (PMID 40362574, 2025). "Furthermore, VDR expression was significantly upregulated in cancer stages 1, 2, 3, and 4, with the highest increase observed in stage 3 compared to that in normal individuals." (PMID 39268267, 2024). "On the contrary, higher nuclear VDR-IRS increased the odds of lymph node involvement, which could suggest direct involvement of VDR in the way the tumor microenvironment prevents (or potentializes) cancer cell invasion." (PMID 39411136, 2024). "We found that the expression of VDR is associated with various clinical features (i.e., age, menopausal status, and NAC cycle number) and characteristics of prognostic significance, such as residual cancer burden class." (PMID 39411136, 2024). "In order to validate the correlation between VDR expression and immune infiltration, the expression of VDR and cell markers including FAP (cancer-associated fibroblast marker), CD68 (macrophage marker) and CD15 (neutrophil marker) in PTC tissues was examined by qRT-PCR." (PMID 38639057, 2024). "VDR expression is widespread across various cell types, including cancer and immune cells." (PMID 38355711, 2024). "For example, cellular models have shown that VDR might potentiate the action of tamoxifen by downregulating the Wnt/β-catenin pathway in MCF-7 cancer stem cells." (PMID 39411136, 2024). "However, many critical translational questions must be explored and answered on the cellular and molecular mechanisms by which VDR prevents the survival of cancer cells and inhibit angiogenesis." (PMID 38318147, 2024). "Indeed, 25D3, when present at high concentrations, induces VDR activities, notably in cancer cells when 1,25D3 production is abolished." (PMID 38785958, 2024). "Therefore, it is unsurprising that vitamin D3/VDR signaling is involved in mineral and bone homeostasis, modulation of growth, cardiovascular processes, cancer prevention, and regulation of immune responses, including autophagy." (PMID 37555855, 2024). "The importance of controlled access of regulatory proteins to the genome has been demonstrated in numerous cancers, and its interplay with the pathways in this study as well as the vitamin D receptor certainly may herald future important findings for VDX-111." (PMID 38771847, 2024). "Using the cBioportal platform, variation of the VDR across different cancers was analyzed." (PMID 39268267, 2024). "This is the first pan-cancer analysis of VDR and the results provide new insights into the relationship between VDR and various types of cancers, thus may offer comprehensive references for further clinical research." (PMID 38639057, 2024). "VDR is a member of the nuclear hormone receptor superfamily of ligand-inducible TFs, and its downstream targets are principally involved in several metabolic pathways, such as those involved in immune response and cancer." (PMID 39791702, 2024). "Additionally, we explored VDR genetic variation across various cancers using the cBioPortal platform and discovered that amplification mutations were the most prevalent type of VDR mutations, followed by deep deletions." (PMID 39268267, 2024). "The lack of functional studies means that pan-cancer analysis provides correlative data, necessitating functional studies to establish causality and to understand the mechanistic role of VDR in CESC." (PMID 39268267, 2024). "In CRC, VDR has anti-cancer properties and was found to be downregulated in CRC cells and tissues." (PMID 38372868, 2024).
cancer (continued). "Bufalin has been proposed as a valuable tool for exploring VDR regulation by signals originating from the cell membrane and for understanding the pathophysiological mechanisms that link VDR to cardiovascular dysfunction and cancer." (PMID 38318147, 2024). "The vitamin D receptor (VDR) regulates gene expression involved in many physiological processes, including cell growth and differentiation, immune function through T and B lymphocytes, and inflammation, playing a crucial role in anti-cancer defense mechanisms." (PMID 39766100, 2024). "It is presumed that one of the mechanisms through which the VDR inhibits tumoral growth is by maintaining a normal balance between oncogenic and cancer-suppressing lncRNAs, an observation demonstrated in studies on mice that lack the VDR and consequently exhibit a more oncogenic lncRNAs profile." (PMID 38928369, 2024). "VDR activity differs within healthy and cancerous tissue, and between cancer cell lines." (PMID 38732639, 2024). "However, basic studies have tried to answer some of the questions relating to the role of VDR signaling in cancers by showing that VDR knockout results in increased susceptibility to chemicals-induced carcinogenesis." (PMID 38318147, 2024). "In the same cancers, the VDR transcript did not correlate with patient survival, highlighting a specific association of VDR target genes, but not necessarily VDR expression with cancer progression." (PMID 38662827, 2024). "The VDR (vitamin D receptor) gene, also known as NR1I1 and PPP1R163, encodes the vitamin D3 receptor, which regulates a variety of metabolic pathways and thus has anti-cancer effects." (PMID 36902812, 2023). "Besides the widely discussed functions of VitD/VDR in cancer, researchers have been investigating the link between VitD deficiency and the development of OPMD." (PMID 37894739, 2023). "Since VDR expression is conserved in many human cancers, vitamin D3 status may be an important modulator of cancer progression." (PMID 37299554, 2023). "VDR is universally present in most nucleated cells at variable concentrations and is expressed in virtually all tissues, including bone, colon, breast, ovary, lung, kidney, immune cells and even cancer cells, exerting a broad spectrum of functions." (PMID 37046222, 2023). "Overall, studies conducted to date agree that VDR hypermethylation may favor cancer onset and progression." (PMID 38203278, 2023). "Vitamin D (VitD) and its receptor (VDR) have been intensively investigated in many cancers." (PMID 36902107, 2023). "β-catenin shRNA contributed oppositely to cancer cell activity with VDR shRNA." (PMID 37046222, 2023). "However, the role of VDR in the mediation of vit-D3 anti-cancer effects remains controversial and should be established in BC cells." (PMID 37835527, 2023). "For instance, vit-D3/VDR complexes were shown to impair and inhibit anti-cancer cytokine networks, which are responsible for the recognition and elimination of malignant cells, including tumor necrosis factor (TNF)/nuclear factor-ķB (NF-ķB) signaling systems." (PMID 37835527, 2023). "VDR overexpression inhibited invasion but promoted apoptosis in cancer cells." (PMID 37046222, 2023). "Overall, the findings of this study suggest that modulating VDR signaling during key stages of cancer and tissue injury may be important from a therapeutic perspective." (PMID 37228489, 2023). "This study found that the association between polymorphisms in the Vitamin D receptor and cancer development was insignificant, but no research was done correlating identified polymorphisms in Vitamin D to response to treatment." (PMID 37878192, 2023). "Multiple mechanisms by which VDR affects cancers have been found." (PMID 37074210, 2023). "Clearly, research on intestinal VDR provides a framework to understand how intestinal dysfunction may inadvertently promote the development of distant cancer." (PMID 37074210, 2023).
cancer (continued). "Additionally, the clinical significance of VDR overexpression is controversially discussed for different cancer entities, suggesting both tumor-promoting and tumor-suppressing activities." (PMID 36291915, 2022). "Vitamin D receptor (VDR) is widely distributed in many kinds of cells, and it participates in regulating multiple pathophysiologic processes, such as anti-inflammation activities, infection prevention, and cancer prevention." (PMID 35047105, 2022). "Furthermore, a low VDR expression and altered vitamin D metabolism reduced the vitamin D anti-cancer effects." (PMID 36362766, 2022). "Vitamin D, signaling through VDR, is also known to have a protective effect against some cancers." (PMID 35406129, 2022). "We next tested if ‘ligand-dependent’ VDR activation by VitD/analogs in combination with chemotherapeutic stressors, such as cisplatin, may even trigger cancer cell death of cisplatin-resistant cells." (PMID 36291915, 2022). "However, VDR expression had been evaluated in healthy tissues, as well as diverse primary cancer cells in various studies." (PMID 36362766, 2022). "In summary, the broad spectrum of anti-cancer actions by active VDR can be seen." (PMID 36364774, 2022). "Additionally, a low VDR expression in various primary tumours has been associated with aggressive tumour characteristics and poor differentiation, suggesting that VDR-mediated 1,25(OH)2D3 actions are dysregulated in cancer cells." (PMID 36362766, 2022). "Interestingly, some studies suggest that the VDR itself possesses a ligand-independent function affecting cancer growth and the metastatic potential." (PMID 36362766, 2022). "VDR agonists can inhibit the cell cycle of a variety cells, especially cancer cells." (PMID 35734414, 2022). "This intracellular hormone receptor affects cell growth and differentiation, embryonic development, and metabolic homeostasis by binding to the biologically active form of vitamin D. VDR is also essential for cell signaling pathways, which play a role in the development of many cancers." (PMID 35996514, 2022). "The development of calcitriol analogs that show less specificity for CYP24A1 but elicit strong VDR responses could be a solution for the low availability of calcitriol at the cancer site." (PMID 35406562, 2022). "Methylation of VDR has been shown in different cancer types." (PMID 36246903, 2022). "The degradation of calcitriol abrogates the VDR signaling and promotes the cancer progression." (PMID 36527000, 2022). "Consequently, the VDR-mediated transcription of 1,25(OH)2D3-sensitive genes, which confer vitamin D anti-cancer effects, was reduced." (PMID 36362766, 2022). "However, research on pleiotropic effects of vitamin D has found that the VDR is expressed in a variety of tissues, including malignant tumors." (PMID 35631448, 2022). "miR-125b is not the only molecule that regulates the level of the vitamin D receptor, as miR-27b also binds at the 3 ‘UTR site of the gene for the classic vitamin D receptor, reducing its expression, which was observed in cancer cells of the pancreas and colon." (PMID 35563410, 2022). "A tissue-specific manner of VDR expression has been shown in childhood cancer patients." (PMID 35884356, 2022). "In addition to the well-established ER and PR, other NRs, including retinoid X receptor (RXRα), peroxisome proliferator-activated receptor (PPAR), vitamin D receptor (VDR), and others, play notable roles in the pathophysiology of BC and other cancer entities." (PMID 35406808, 2022). "Relevant data show that VDR has a protective effect on the gut; it may maintain gut homeostasis and prevent cancer by regulating the JAK/STAT pathway." (PMID 36014889, 2022). "Since we discovered that TGFβ was able to induce the expression of VDR, we wondered whether vitamin D could be effective in reducing TGFβ-triggered transition, even in our cancer models insensitive to the antiproliferative action of the hormone." (PMID 34208208, 2021).
cancer (continued). "Interestingly, HSF1, HIF1α, RXR, and VDR have been described as CAF modulators in various cancer types." (PMID 33670717, 2021). "Second, the results of the present study may illustrate the discrepancies that exist in the findings of different studies regarding vitamin D, VDR, and cancer by considering both genetic and environmental aspects simultaneously." (PMID 34727991, 2021). "However, in many type of cancer cells this VDR and CYP27B1-mediated regulation is disturbed which leads to disorders of vitamin D metabolism and action." (PMID 34208589, 2021). "We recently reported VDR protein expression in canine mammary tissue, with lower VDR expression in malignant tumours (26.5 %), followed by benign (40.0 %) and normal glands (100.0 %).The present study corroborates our previous findings, since 27.6 % of CMCs expressed the VDR protein." (PMID 34034728, 2021). "In this review, I will examine the role of VDR in hair follicle cycling and cancer resistance along with the concept that the unliganded VDR may regulate gene transcription in a manner different from what the liganded receptor would do." (PMID 34950833, 2021). "Epigenetic silencing of VDR has been also observed in cancer." (PMID 34208589, 2021). "The engagement of microRNA in the control of VDR expression in cancer has also been proposed." (PMID 34208589, 2021). "There are many variables that can directly alter VDR function, and the presence of genomic alterations in cancer cells could indirectly deregulate target gene responses to 1,25D or downstream pathways (such as proliferation or apoptosis)." (PMID 34950835, 2021). "In these cases, a partial blockade of the VDR by pathogens could be another pathway within the established infectious etiology of cancer." (PMID 33897704, 2021). "In one study, VDR-null mice were more likely to develop carcinogen-induced cancer." (PMID 33440610, 2021). "However, even though this seems to be beneficial in the early stages of cancer, it has been shown that during tumour progression cancer cells can downregulate VDR and become resistant to vitamin D complements." (PMID 33060625, 2020). "Since TLR polymorphisms have been associated with changes in susceptibility to many diseases, including cancers and TLRs promote the survival of cancer cells, we also correlated the coexistence of previously genotyped TLR (TLR2, TLR4 and TLR9) polymorphisms with the VDR polymorphisms." (PMID 32471257, 2020). "In cancer, the vitamin D response always regulates the expression level of VDR." (PMID 32679655, 2020). "To this end, we aimed to investigate four single nucleotide polymorphisms (SNPs)—TaqI, ApaI, FokI and BsmI—of the VDR gene within patients with sporadic CRC, for the first time in the Greek population, and to evaluate their association with the risk of cancer development and progression." (PMID 32471257, 2020). "The VDR is a superfamily of nuclear hormone receptors interacting with vitamin D. Vitamin D and VDR regulate multiple pathophysiological pathways, including calcium phosphorus metabolism, anti-inflammation, and cancer prevention, proliferation and differentiation." (PMID 32538430, 2020). "Using a genetically modified mouse model resuming characteristics of human prostate tissue in the early stages of tumor development, authors demonstrated that the absence of VDR was associated with larger cancer foci development." (PMID 32560347, 2020). "Over 60 single nucleotide polymorphisms (SNPs) of the VDR gene, located in the promoter region in exons 2–9, both in their proximity and in the 3’-UTR (3’-untranslated) region, have been studied in relation to cancer occurrence and prognosis." (PMID 32471257, 2020). "The multiple effects of VD/VDR include maintaining mineral homeostasis and regulating inflammatory, immune responses and may improve response to cancer." (PMID 32766307, 2020).